LINC00989 (long independently transcribed non-coding RNA 989)
Gene: Long non-coding RNA gene on chromosome 4 (79,491,802 to 79,623,479, forward strand). Ensembl gene ENSG00000250334.
Diseases named in the same sentence as LINC00989 in open-access papers:
LINC00989 is named in the same sentence as 4 diseases in open-access papers, as found by Europe PMC text mining. Sharing a sentence is not in itself a finding about the gene and the disease. The quoted sentences say what the papers report.
breast carcinoma (1 paper, 2023). "LINC00989 was confirmed to be associated with the OS prognosis of patients with breast cancer and hepatocellular carcinoma." (PMID 36737692, 2023).
cancer (3 papers, 2020 to 2026). A tumor composed of atypical neoplastic, often pleomorphic cells that invade other tissues. "LINC00989 is a long non-coding RNA that functions as a tumor suppressor in various cancers, primarily participating in tumor progression through regulation of platelet function and immune responses." (PMID 41570022, 2026). "A previous study on the RNA expression of tumor-educated platelets (TEPs) revealed that the expression level of both RGS18 and LINC00989 was lower in platelets from cancer patients than in those from healthy donors." (PMID 34827689, 2021). "LINC00989 and MAPI-IT1 are associated with congenital diseases, and their relationship with cancer remains unclear." (PMID 32908814, 2020).
LINC00989 also shares sentences with these, for which no sentence is quoted: tumor (2 papers); hepatocellular carcinoma (1).